ACOT1 (acyl-CoA thioesterase 1)
Diseases named in the same sentence as ACOT1 in open-access papers (continued):
Sharing a sentence is not in itself a finding about the gene and the disease.
cancer (6 papers, 2017 to 2025). A tumor composed of atypical neoplastic, often pleomorphic cells that invade other tissues. "Above findings provide direct functional evidence that ACOT1 plays a critical role in mediating piperine's anti-cancer effects, confirming our proposed mechanistic pathway." (PMID 40855327, 2025). "Our identification of piperine as the principal bioactive component responsible for ACOT1 inhibition and anti-cancer effects provides a critical link between traditional phytotherapeutic approaches and modern targeted therapies." (PMID 40855327, 2025). "Additionally, ACOX3, ACAD9, ACAD10, ACOT1, ACOT8, and DECR2 displayed positive associations with PEBP1/STK11 co-expression across various cancer types, highlighting a potential involvement in enhancing fatty acid metabolism in the context of PEBP1/STK11 expression." (PMID 40806276, 2025). "LRRFIP2, WDR82 and ACOT1 were not identified previously as possible biomarkers for any type of cancer." (PMID 29285267, 2017).
tumor (5 papers, 2019 to 2025). "Consistent with our bioinformatic predictions, elevated ACOT1 expression positively correlated with increased tumor malignancy." (PMID 40855327, 2025). "The results showed that ACOT1/2/8/11/13 were significantly downregulated in ccRCC tissues compared to that in adjacent non-tumor kidney tissues in all of these datasets, and in particular, the levels of ACOT11 were markedly reduced in almost every matched normal-tumor pair." (PMID 33362855, 2020). "Met, Itsn1, and Acot1 all show a pivotal role in tumor development; however, the role of these genes in MDSCs is currently unknown." (PMID 32290071, 2020). "Although the concentration of plasma TGs and the expression of acyl-CoA thioesterase 1 (Acot1), a downstream target gene of PPARα, were affected equally when mice were treated with the three PPARα agonists, these ligands showed different actions on tumour suppression and AA metabolism." (PMID 31791289, 2019).
infection (2 papers, 2022 to 2025). The state of being infected such as from the introduction of a foreign agent such as serum, vaccine, antigenic substance or organism. "As ACOT1 and ACOT2 are splice variants, these data suggest that functional differences and substrate specificities due to the location (cytosol and mitochondria, respectively) of these proteins may account for the differences in DENV2 infection phenotype." (PMID 35215835, 2022).
cardiac disease (1 paper, 2025). "Work in young models of cardiac disease has demonstrated a protective role for Acot1 in cardiac remodeling and cardiac energy production." (PMID 39297345, 2025).
neurological diseases (1 paper, 2025). "The increase of ACOT1 in our experiment may establish a link with neurological diseases." (PMID 41244708, 2025).
ACOT1 also shares sentences with these, for which no sentence is quoted: atherosclerosis (1 paper); breast tumor (1); dementia (1); eosinophilia (1); geographic atrophy (1); lung adenocarcinoma (1); lymph node metastasis (1); Myocardial fibrosis (1); osteoporosis (1); Type 1 diabetes (1); vitiligo (1).